TRAV41 (T cell receptor alpha variable 41)
Description:
V region of the variable domain of T cell receptor (TR) alpha chain that participates in the antigen recognition. Alpha-beta T cell receptors are antigen specific receptors which are essential to the immune response and are present on the cell surface of T lymphocytes. Recognize peptide-major histocompatibility (MH) (pMH) complexes that are displayed by antigen presenting cells (APC), a prerequisite for efficient T cell adaptive immunity against pathogens. Binding of alpha-beta TR to pMH complex initiates TR-CD3 clustering on the cell surface and intracellular activation of LCK that phosphorylates the ITAM motifs of CD3G, CD3D, CD3E and CD247 enabling the recruitment of ZAP70. In turn ZAP70 phosphorylates LAT, which recruits numerous signaling molecules to form the LAT signalosome. The LAT signalosome propagates signal branching to three major signaling pathways, the calcium, the mitogen-activated protein kinase (MAPK) kinase and the nuclear factor NF-kappa-B (NF-kB) pathways, leading to the mobilization of transcription factors that are critical for gene expression and essential for T cell growth and differentiation. The T cell repertoire is generated in the thymus, by V-(D)-J rearrangement. This repertoire is then shaped by intrathymic selection events to generate a peripheral T cell pool of self-MH restricted, non-autoaggressive T cells. Post-thymic interaction of alpha-beta TR with the pMH complexes shapes TR structural and functional avidity.
Synonyms: TCRAV19S1; TCRAV41S1
Gene: T-cell receptor variable (V) gene on chromosome 14 (22,320,188 to 22,320,691, forward strand). Ensembl gene ENSG00000211820.
Subcellular location: Cell membrane
Gene Ontology:
Cellular component: plasma membrane
Homologues: Orthologues: chimpanzee TRAV41 (80% identical), macaque TRAV41 (77% identical). Paralogues in human: TRAV22 (42% identical).